IL4 (interleukin 4)
Diseases named in the same sentence as IL4 in open-access papers (continued):
Sharing a sentence is not in itself a finding about the gene and the disease.
tumor (continued). "In the present study, the levels of IL-2 and IFN-γ were significantly increased, but the levels of IL-4 were reduced by hLF in tumor-bearing mice." (PMID 24520300, 2014). "In vitro studies have shown that IL-4 triggers tumor growth of HNSCC cell cultures in a dose-dependent manner." (PMID 25120668, 2014). "The comparison between serum samples of tumor patients and the control group showed significantly elevated serum levels of osteopontin, IL-4 and IL-6." (PMID 25120668, 2014). "Treatment with Ad-hLF increased the levels of serum interferon-γ, serum interleukin-2 (IL-2) and tumor necrosis factor-α, and decreased the levels of serum IL-4 in tumor-bearing mice." (PMID 24520300, 2014). "Many studies carried out in the 1990s and early 2000s demonstrated that tumors or tumor cell lines engineered to produce IL-4 would exhibit increased rejection and retarded growth in vivo; curiously a phenotype often dependent on CD8+ cytotoxic T cells." (PMID 25101088, 2014). "Training alone did not significantly affect IL-4 levels; by contrast, the presence of a tumor tended to increase the IL-4 concentration." (PMID 24520305, 2014). "CD4+ T cell-derived IL-4 has been reported to induce granulocyte infiltration, thereby promoting tumor clearance (an action enhanced by IL-13), and conversely increase tumor cells’ resistance to apoptosis by up-regulation of anti-apoptotic proteins." (PMID 25101088, 2014). "The T cell proliferates in response to autocrine signals from IL-2 and IL-4 resulting in an anti-tumor effect." (PMID 26056588, 2014). "Collectively, these data strongly suggest that within the tumor microenvironment, some mouse γδ T cell populations express IL-4, IL-10, and TGF-β and inhibit the anti-tumor immune response." (PMID 25538706, 2014). "Tumor cells use a variety of different pathways to achieve this goal including overexpression of certain cytokines (IL-4, IL-10, TGFB), catabolic enzymes such as indoleamine 2,3 dioxygenase, and also by upregulation of surface PD-L1 expression." (PMID 24551119, 2014). "A decreased CD8+ T cell proliferation was detected upon co-cultivation of T cells with IL-4 pretreated as well as with IL-4 and TNFα pretreated tumor cells." (PMID 24885059, 2014). "Patients were vaccinated with monocyte-derived DCs pulsed with tumor lysate or a mix of tumor-related peptides, and stimulated with GM-CSF and IL-4." (PMID 24743024, 2014). "In the tumor tissues biopsies analysed, IL-4, IL-10, and TGF-β1 were the main cytokines expressed and their expression was maintained during growth of the tumor." (PMID 24808638, 2014). "Mechanistically, COX-2 expression blunted the interferon-gamma release of antigen-specific T cells exposed to their respective cellular targets, and increased the expression of interleukin-4 and indoleamine 2,3-dioxygenase by tumor cells." (PMID 25501829, 2014). "Macrophages activated by IL-4, IL-13, and IL-10 are referred to as M2 macrophages, which can suppress inflammation, induce angiogenesis, promote tissue repair, and enhance tumor growth." (PMID 24580730, 2014). "iNKT-cell activation will cause release of IL-4 and IL-13, which are both known to elicit MDSC recruitment and infiltration as well as direct suppression of tumor-specific CD8+ T-cells." (PMID 24949488, 2014). "The Th2 subgroup predominantly releases IL-4 and IL-10, which are involved in the inhibition of the immune system, preventing the human body from killing tumor cells." (PMID 25202391, 2014). "ICAM1 expression was highly upregulated upon combined IL-4 and TNFα treatment, which can support T cell/tumor interaction." (PMID 24885059, 2014). "In animal models, antagonistic antibodies against IL-4 or agonistic anti-CD40 favor anti-tumor Th1 functions." (PMID 23577028, 2013). "More recently, however, the preferred method of obtaining immature DCs is from peripheral blood CD14+ monocytes under tumor-free conditions, which are subsequently treated with GM-CSF and IL-4." (PMID 23606870, 2013).
tumor (continued). "IL-27 has also been shown to enhance IL-10 production and negatively regulate IL-4 and IL-17, however, subtle effects of Il27ra genotype were observed for these cytokines in the tumor models." (PMID 23554861, 2013). "In contrast, although there was a trend toward increased numbers of IL-4 and IL-17 producing tumor antigen-specific CD4 T cells both systemically and locally, these trends were not statistically significant." (PMID 23557194, 2013). "The findings reveal that AGE increased the level of IFN-λ and IL-4 cytokines producedby splenocytes stimulated by specific tumor antigen and decreased the number ofTreg cells in the spleen (p<0.05)." (PMID 23700559, 2013). "Our data suggest overriding immune suppressive effects of IL-10 in tumor-conditioned skin and argue in favor of the incorporation of GM-CSF and IL-4 in adjuvants for transcutaneously or intradermally delivered cancer vaccines." (PMID 23875023, 2013). "Although we are unaware of any published evidence implicating DUSP6 or SPINT2 as tumor suppressors in B lymphoid malignancies, their expression was found to be increased in our experiments where IL-4 impaired EBV-induced transformation." (PMID 23724103, 2013). "Interleukin 4 (IL-4) was shown to be tumor-promoting in full carcinogenesis studies using 3-methylcholanthrene (MCA)." (PMID 24403255, 2013). "The IL4 pathway was significantly enriched in both signatures of tumor progression and chemotherapy." (PMID 23451142, 2013). "It would be very interesting to investigate the effect of treatment with the IL-4 mutein pitrakinra on human CRC cell tumour xenograft growth in nude mice, in the first instance." (PMID 23784081, 2013). "Of interest, in vivo tumor models involving IL-4 also exhibited Th1 cell immunity as well as significant eosinophil influx, tumor rejection/suppression, and prolonged survival of the host." (PMID 22251275, 2012). "Disruption of the basement membrane by islands of tumor cells protruding into the gel was observed in murine OTCs with macrophages cultured in presence of IL-4, while corresponding OTCs in the human setup showed a generally reduced basement membrane staining." (PMID 22792213, 2012). "Additional in vivo research revealed that IL-4-producing Th2 cells were critical for natural killer cell activation (perforin, granzyme-B) and tumor rejection." (PMID 22251275, 2012). "IL-4 stimulation of macrophage-containing cultures resulted in enhanced tumor cell invasion evidenced by degradation of the basement membrane, enhanced collagenolytic activity and increased MMP-2 and MMP-9." (PMID 22792213, 2012). "Additionally, the Th2 response could directly participate in colitis-associated tumor initiation since Th2-related cytokines (i.e., IL-4 and IL-13) increase the expression of activation-induced cytidine deaminase (AID), an enzyme, which induces DNA mutation in cultured colonic epithelial cells." (PMID 23109839, 2012). "Tumor promoting effects are mediated by M2 polarized macrophages that can be differentiated by IL-4 in vivo and in vitro." (PMID 22792213, 2012). "DCs found within tumour infiltrates are commonly “frozen” in an immature status (iDCs) by soluble factors of the tumour milieu such as IL-4, IL-6, GM-, and M-CSF." (PMID 22400028, 2012). "Tumour necrosis factor-α, interferon-γ and interleukin-4 are critical cytokines in regulating the immune responses against infections and tumours." (PMID 22547990, 2012). "Another in vivo murine study demonstrated that IL-4-mediated tumor suppression involved the production of the cytokine interferon-gamma (IFN-γ), which supports subsequent findings indicating that IL-4-transfected tumor cell vaccines promoted Th1 immunity." (PMID 22251275, 2012). "Both naïve and tumor-educated macrophages produced significantly more IGF-1 after IL-4 treatment; tumor-educated macrophages more than doubled IGF-1 output compared to naïve samples (green bars)." (PMID 21699731, 2011).
tumor (continued). "One mechanism by which IL-4 appears to enhance the survival of tumor cells is through a direct anti-apoptotic effect." (PMID 24213139, 2011). "Increased resistance to cytotoxic molecules, such as perforin, decreased tumour antigen expression and secretion of immunosuppressive factors, such as IL-4, IL-10 and transforming growth factor-β1 are alternative (or concurrent) mechanisms of immune escape." (PMID 21811598, 2011). "IL-4 is produced by tumor-infiltrating CD4 T cells and there is mounting evidence of its relevance in the polarization of macrophages with pro-tumor functions." (PMID 24213109, 2011). "DC were derived from CD14+ monocytes in the presence of GM-CSFand IL-4 and during this process we had observed that tumor-derived compoundsimpair differentiation." (PMID 21423807, 2011). "Taken together, these studies highlight the complex role played by IL-4 in modulating tumor immunity." (PMID 24213139, 2011). "IL-4 potently stimulates alternative macrophage activation, and is more abundant in tumor-bearing lungs than naïve." (PMID 21699731, 2011). "On the contrary, a significant increase in serum IL-4 levels was observed only in tumor-bearing WT mice (p<0.01)." (PMID 21484786, 2011). "IL-4 stimulated naïve and tumor-educated MØCM significantly augmented LM2 proliferation (green bars), with IL-4 treated tumor-educated MØCM being the most potent." (PMID 21699731, 2011). "Broadly speaking however, it appears that supra-physiological production of IL-4 within the tumor microenvironment promotes tumor rejection." (PMID 24213139, 2011). "Further, it has been recently shown that the cathepsin protease activity of IL-4-stimulated TAM promotes tumor invasion." (PMID 24213109, 2011). "Monocyte-derived DCs were generated during 4 days of culture with recombinant granulocyte-macrophage colony stimulating factor and interleukin-4, and pulsed with tumor lysate produced by hypochlorous acid oxidation of tumor cells." (PMID 22082029, 2011). "Interestingly, IL-4 transduced cancer cells display increased lesional infiltration by DCs relative to other cytokines, which may result in enhanced cross-presentation of tumor-associated antigens by DCs." (PMID 23493491, 2011). "By contrast, when lower levels of IL-4 are produced by infiltrating leukocytes, pro-tumor effects are dominant and disease progression ensues." (PMID 24213139, 2011). "It has also been reported that human CD4+ regulatory NKT cells can suppress the expansion of tumor antigen-specific CTLs via Th2 cytokines such as IL-4 and IL-10." (PMID 20052413, 2010). "One case reported long-term survival of three years in a patient with recurrent malignant glioma following intratumoral infusion of IL4-PE with a durable tumor response." (PMID 22069569, 2010). "A case is made that the FAAH-IR is regulated by the tumour microenvironment, and a potential candidate molecule, IL-4, has been investigated in vitro, although contributions by other components of the tumour environment should certainly be considered." (PMID 20808855, 2010). "IL-4 acts as an inhibitor of tumor growth, but its mechanism of action likely varies with different tumor cells." (PMID 20445741, 2010). "TGFβ and TNFRsf1a displayed high expression in both tumor cell compartments, while IL-4 and IFNγ had low expression levels." (PMID 20525400, 2010). "By linking EGF and IL-4, two well-known tumour-targeting ligands, to a truncated pseudomonas exotoxin A molecule, we created a novel recombinant agent that showed potent in vitro and in vivo activity." (PMID 19755995, 2009). "According to Argarwal and colleagues, early stage of oral SCC expressed mainly INF-γ and IL-2 genes (Th1 responses), whereas the advanced stage tumours presented IL-4 and IL-10 expression (Th2 response)." (PMID 20049171, 2009).
tumor (continued). "The fact that unpulsed DCs can induce T cells to produce large amounts of cytokines (IFN-γ and IL-4) and protect mice from tumour challenge has implications for the use of DCs in immunotherapy." (PMID 18253127, 2008). "After administration of the complete mixture of FO, SOM and high protein/leucine to the tumour-bearing mice, IL-4 production in both ConA-stimulated whole blood and splenocytes showed a significant increase (P<0.025)." (PMID 19018259, 2008). "Probably directed in part by PGE2, based on reduced production of anti-tumor Th1 cytokines (TNFα, IFNγ and IL-2) and increased production of Th2 cytokines (IL-4, IL-10 and IL-6)." (PMID 19455240, 2007). "IL-2 and IL-13 were not correlated with PR status, whereas IL-1β, IL-6, IL-8, IL-10, IFN-γ, MCP-1, MIP-1β, TNF-α and, to a lesser extent, IL-4, IL-12 and G-CSF were more abundant in PR-negative tumours than in PR-positive ones." (PMID 17261184, 2007). "Like other inflammatory cells, mast cells are attracted to tumors by various factors, including hypoxia, cellular damage, tissue ischemia and tumor-derived chemoattractants, including stem cell factor, interleukins-3 (IL-3) and IL-4." (PMID 17177999, 2006). "They in turn produce various cytokines, such as tumor necrosis factor-α (TNF-α), IL-1, IL-4 and IL-6, which can induce apoptosis of tumor cells." (PMID 17177999, 2006). "Such tumour-produced molecules, including IL-4, IL-6, IL-10, CSF-1, TGFβ and prostaglandin E2 (PGE2), and TAM-produced factors such as IL-10 and PGE2, contribute to the general immunosuppression of the host as well as the antitumour activity of macrophages." (PMID 15164120, 2004). "Two colour flow cytometric analysis of intracellular IFN-γ and IL-4 expression by CD8+ T cells demonstrated that tumour-specific T cells from USPC patients 1 and 2 showed a major Type 1 bias in cytokine expression." (PMID 11857027, 2002). "Transduction of B16F10 cells (MHC class I and II negative) to express either IL-2 or IL-4 alone delays the formation of tumours, IL-4 being more effective than IL-2." (PMID 8679459, 1996). "The recent use of interleukin 2 (IL-2) and interleukin 4 (IL-4) single cytokine modified tumour cells in rodent models has demonstrated a potential use of these cytokines to produce autologous cancer cell vaccines." (PMID 8679459, 1996). "Treatment of established tumours with a single injection of lethally irradiated tumour cells expressing IL-2 + IL-4 was sufficient to either reject tumours, or at least delay further tumour development." (PMID 8679459, 1996). "In comparison, when cells expressing combined IL-2 + IL-4 were injected there were more granulocytes present, and perhaps more importantly, these were mainly localised within the tumour." (PMID 8679459, 1996). "Engineering of a variety of rodent tumour cells to secrete either interleukin 2 (IL-2), or interleukin 4 (IL-4), has been demonstrated to reduce their tumorigenicity." (PMID 8347485, 1993). "Conversely, upregulation of proteins involved in IL-4 and IL-13 signaling might indicate immune response modulation, possibly enhancing anti-tumor immunity or altering the tumor microenvironment." (PMID 39949745, 2025). "Furthermore, a reduction in tumour-associated macrophages (TAMs), regulatory T lymphocytes (Tregs), vascular endothelial growth factor (VEGF), interleukin-4 (IL-4) and interleukin-6 (IL-6), which have immunosuppressive effects, was observed in BC." (PMID 41301715, 2025). "Moreover, Arg1 expression in TAMs is sustained by a complex tumor milieu, including IL-4/IL-13, IL-10, TGF-β, lactic acid, hypoxia, and metabolic crosstalk, which is not fully recapitulated by IL-4 alone in vitro." (PMID 41465516, 2025). "Regarding mechanism, IL-33 activates the p38- GATA binding protein 3 (GATA3) signaling pathway to induce M2 polarization of macrophages, promote Th2 cells and ILC2 to secrete tumor-promoting cytokines, mainly IL-4, IL-5, and IL-13, thereby playing a role in promoting tumor development." (PMID 39925809, 2025).
tumor (continued). "At the same time, new avenues for regulating inflammation and restoring anti-tumor immunity may be explored through the development of therapeutic strategies targeting IL-4 or its receptors, such as IL-4 antagonists, ADCs or small molecule inhibitors." (PMID 41376630, 2025). "Moreover, over a third of mice treated with IL-4+ gBT.I cells were either complete or partial responders 120 days after tumor engraftment." (PMID 40367186, 2025). "Additionally, FPR2 influences the tumor microenvironment by stimulating the secretion of Th2 cytokines, such as IL-4 and IL-10, which drive the polarization of macrophages into the M2 phenotype." (PMID 40330466, 2025). "The increase in inflammatory status, combined with the release of tumor-associated antigens induced by the treatment, implies the activation of CD137+ T cells, particularly CD4+CD137+ T cells, which secrete the pro-inflammatory cytokine interleukin 4 (IL-4)." (PMID 41428121, 2025). "Although we could not detect IL-4 mRNA in our data, the loss of ILC2s in IFNhighT2low tumors suggests that these cells may be a critical source of tumor IL-4 in our model." (PMID 40367186, 2025). "Studies have shown that the IL-4 signaling may promote tumor immune escape by activating CD4+ regulatory T cells (Tregs) and inhibiting the function of NK cells." (PMID 40656893, 2025). "However, a high proportion of Th2 infiltration has been demonstrated to increase IL-4 levels in basophil-enriched tumor-draining lymph nodes, which is correlated with poor tumor prognosis." (PMID 40599993, 2025). "Additionally, γδ T cells usually produce higher amounts of anti-tumor cytokines (such as TNF and IFN-γ) than pro-tumor cytokines (for instance: IL-4, IL-10, IL-17, IL-22, and IL-35) within the TME, reflecting their prognostic value in cancer patients." (PMID 40148988, 2025). "Depending on their subtype, TAMs can produce either pro-inflammatory cytokines (e.g., IL-1β and IL-6) or anti-inflammatory cytokines (e.g., IL-4 and IL-10), thereby modulating the cytokine profile and shifting the tumor microenvironment toward either tumor suppression or tumor promotion." (PMID 40308575, 2025). "In addition, M2a macrophages can assist tumor cells in growth through the IL-4/STAT6-mediated pathway, and IL-4 released by tumor cells and M2a macrophages further promotes the polarization of M2 macrophages into M2a, thus forming a positive feedback pathway." (PMID 40703527, 2025). "Most studies indicate that IL-4 correlates with GBM tumor regression, although the mechanism remains unclear." (PMID 40497976, 2025). "Once activated, iNKT cells secrete a diverse array of cytokines, including IFN-γ and IL-4, among others, which not only mediate direct tumor cytotoxicity but also enhance the recruitment and activation of other immune cells, such as dendritic cells (DCs) and CD8+ T cells." (PMID 39941775, 2025). "Furthermore, we found that the mutation carriers showed high expression levels of genes enriched in IL-4 production and negative regulation of the immune system process, suggesting an immunosuppressive potential for tumor growth." (PMID 40873563, 2025). "This indicates that IL-4 may exert anti-tumor activity by affecting the proliferation, apoptosis, and migration of PC cells." (PMID 39958351, 2025). "In colon cancer, IL-4 and IL-6 promote tumor growth and metastasis." (PMID 40307509, 2025). "Additionally, neutrophils can influence DCs to adopt a pro-tumor phenotype by promoting the secretion of immunosuppressive cytokines like IL-10 and IL-4, further dampening anti-tumor immunity." (PMID 40486614, 2025). "Immunization by electroporation with 30 μg of a DNA plasmid encoding MAGE-A3 isoform significantly enhanced Th1 (IgG2a, IFN-γ) and Th2 (IgG1, IL-4) responses, and delayed tumor growth when compared to mice immunized with empty vector in the murine lung cancer LLC model." (PMID 41012179, 2025).